RELT (RELT TNF receptor)
Description:
May play a role in apoptosis. Induces activation of MAPK14/p38 and MAPK8/JNK MAPK cascades, when overexpressed. Involved in dental enamel formation.
Synonyms: TNFRSF19L; FLJ14993; AI3C; TRLT
Tractability: Antibody: UniProt places it where antibodies can reach, with high confidence; UniProt predicts a signal peptide or a membrane-spanning region; its Gene Ontology location is reachable by antibodies, with medium confidence. PROTAC: ubiquitination databases record sites on it.
Gene: Protein-coding gene on chromosome 11 (73,376,325 to 73,397,474, forward strand). Ensembl gene ENSG00000054967.
Subcellular location: Cell membrane; Cytoplasm; Cytoplasm, perinuclear region
Subcellular location (Human Protein Atlas): Cytosol; Nucleoli; Nucleoplasm
Gene Ontology:
Molecular function: protein binding
Biological process: amelogenesis; apoptotic process
Cellular component: cytoplasm; cytosol; plasma membrane; perinuclear region of cytoplasm
Genetic constraint (gnomAD): Loss-of-function variants: 36 observed, 49.78 expected, observed/expected ratio (o/e) 0.72, 90% interval 0.55 to 0.95. The upper end of that interval is the gene's LOEUF score, 0.95, which puts it in group 4 of 6, group 1 being the genes least tolerant of losing a copy. Missense variants: 503 observed, 564.96 expected, observed/expected ratio (o/e) 0.89, 90% interval 0.83 to 0.96. Synonymous variants: 229 observed, 232.85 expected, observed/expected ratio (o/e) 0.98, 90% interval 0.88 to 1.1.
Homologues: Orthologues: chimpanzee RELT (99% identical), macaque RELT (94% identical), mouse Relt (86% identical), dog RELT (85% identical), rat Relt (84% identical), guinea pig RELT (82% identical), rabbit RELT (81% identical), pig RELT (81% identical), tropical clawed frog RELT (44% identical), zebrafish relt (39% identical). Paralogues in human: TNFRSF21 (16% identical), NGFR (14% identical), LTBR (13% identical), TNFRSF8 (13% identical), TNFRSF11A (12% identical), TNFRSF1A (12% identical), TNFRSF1B (12% identical), TNFRSF9 (12% identical), CD40 (12% identical), TNFRSF11B (12% identical), TNFRSF6B (12% identical), TNFRSF25 (11% identical), and 9 more.
Diseases named in the same sentence as RELT in open-access papers:
RELT is named in the same sentence as 40 diseases in open-access papers, as found by Europe PMC text mining. Sharing a sentence is not in itself a finding about the gene and the disease. The quoted sentences say what the papers report.
breast carcinoma (7 papers, 2008 to 2024). "Nevertheless, the identification of RELT autoAbs as a potential biomarker for breast cancer in one study is consistent with RELT being either mutated or expressed at higher levels in breast cancer to invoke an immune response." (PMID 37893069, 2023). "In the present study we identified three breast tumor-associated proteins – ASB-9, SERAC 1 and RELT – from a breast cancer cDNA T7 phage library screening with antibodies in breast cancer sera." (PMID 18460216, 2008). "Current evidence indicates that RELT is a tumor-associated antigen upregulated in breast cancer, although it is unclear whether there is a causal association between RELT and breast cancer." (PMID 37893069, 2023). "Unexpectedly, RELT protein was expressed at higher levels in breast cancer (BC) cell lines in comparison to cell lines of the hematopoietic system." (PMID 39767574, 2024). "This is an interesting finding, since it can be potentially used as a target to inhibit cell invasion of HER2-positive breast cancer cells by reversing EMT or inducing RELT." (PMID 32947764, 2020). "Each of the three TAAs, ASB-9 (36/87 (41.3%), P = .0112), SERAC1 (41/87 (47.1%), P = .0009), and RELT (46/87 (52.9%), P = .0001) elicited significantly higher frequency of AAbs in breast carcinoma patients compared to healthy controls." (PMID 21423545, 2011). "Serum RELT (soluble) was elevated in patients with gastric cancer and breast cancer, especially in B-cell lymphomas, but RELT is an orphan receptor, and its ligand is unknown." (PMID 38951916, 2024). "Surface expression of RELT was observed at similar levels in cell lines representing lung cancer (H358) and breast cancer (MCF7 and 231), and it is therefore worth investigating if upregulated RELT can serve as the receptor for chemotherapy delivery systems in patients with breast cancer." (PMID 39767574, 2024). "Further research could help clarify RELT’s role in breast cancer, specifically whether it functions in a tumor-promoting or tumor-suppressing capacity across different BC subtypes." (PMID 39767574, 2024). "RELT autoantibodies (autoAbs) were identified to be a potential prognostic indicator for the early detection of breast cancer in a study comparing the serum of 87 healthy women and 87 women with varying stages of breast cancer." (PMID 37893069, 2023). "Therefore, in this present investigation, we show that EA plant extract can regulate the RELT/EMT event and inhibit cell invasion of the two human HER2-positive breast cancer cell lines." (PMID 32947764, 2020).
gastric cancer (4 papers, 2019 to 2025). A primary or metastatic malignant neoplasm involving the stomach. "In the study of RELT and cancer, we found that RELT was associated with immune infiltration in a variety of cancers, including ESCC, PC (prostate cancer), HCC (hepatocellular carcinoma), lung adenocarcinoma, colorectal cancer, and gastric cancer." (PMID 41376629, 2025). "RELT may serve as a potential biomarker for gastric cancer, as RELT in serum is upregulated approximately 2.7-fold in patients with gastric cancer as measured by both a cytokine antibody array as well as by ELISA." (PMID 37893069, 2023). "It is not clear whether the upregulation of RELT is associated with tumorigenesis of gastric cancer, or whether it is a byproduct of gastric cancer." (PMID 37893069, 2023). "However, it is worth noting that RELT and the IFN gamma receptor were both significantly upregulated in gastric cancer patients versus control subjects, so RELT may not act antagonistically towards IFN-γ signaling in all settings." (PMID 37893069, 2023).
B-cell lymphoma (3 papers, 2023 to 2025). "The HPA confirms higher levels of RELT expression in diffuse cancers of the immune system, such as B-cell lymphoma, leukemias, and myeloma." (PMID 37893069, 2023). "Co-staining of RELT with CD20 indicates that RELT is expressed in malignant B cells, and it has been shown that RELT may be associated with B-cell lymphoma development and progression." (PMID 41376629, 2025). "RELT was upregulated in the lymph nodes of patients with B cell lymphoma versus normal lymph nodes." (PMID 37893069, 2023).
colorectal cancer (3 papers, 2023 to 2025). A primary or metastatic malignant neoplasm that affects the colon or rectum. "RELT activates NF-κB pathway and deregulates β-catenin activity in the majority of sporadic forms of colorectal cancer and colon cancer cell lines." (PMID 38168324, 2023). "Its upstream gene in the identified sub-network, RELT, is frequently overexpressed in colorectal cancer cell lines and primary colorectal carcinomas, consistent with the negative effect of RELT on OS shown in our study." (PMID 38168324, 2023).
esophageal squamous cell carcinoma (3 papers, 2023 to 2025). Esophageal squamous cell carcinoma (ESCC) is a type of esophageal carcinoma (EC) that can affect any part of the esophagus, but is usually located in the upper or middle third. "RELT is also closely associated with cancer, and available reports have shown that increased expression of RELT in esophageal squamous cell carcinoma (ESCC) correlates with a poor prognosis for the patients." (PMID 41376629, 2025). "Conversely, RELT is implicated as an oncogene that inhibited apoptosis in esophageal squamous cell carcinoma (ESCC), as determined by AV/PI staining, and Western blotting of Survivin and cleaved Caspase-3." (PMID 37893069, 2023). "RELT overexpression promotes cell cycle progression in esophageal squamous cell carcinoma (ESCC) through activation of NF-κB and inhibition of p27 and Caspase-3." (PMID 39767574, 2024).
clear cell renal cell carcinoma (2 papers, 2023 to 2025). "The experiment aims to verify the function of Tumor Necrosis Factor Receptor Superfamily Member 19L (RELT) in clear cell renal cell carcinoma (ccRCC)." (PMID 41376629, 2025).
lung carcinoma (2 papers, 2023 to 2024). "The overexpression of RELT in lung cancer was shown to serve as the receptor of nanoparticle delivery of chemotherapeutic agents in a mouse model of lung cancer." (PMID 39767574, 2024). "RELT was identified to be the receptor for the specific delivery of a peptide-conjugated nanoparticle delivery system of drugs to lung cancer tissue in a mouse model." (PMID 37893069, 2023). "RELT mRNA was downregulated 1.9-fold in response to treatment with the anticancer agent romidepsin in at least one patient with lung cancer in this study." (PMID 37893069, 2023).
multiple myeloma (2 papers, 2024). "Next, we collected bone marrow samples from 5 cases of multiple myeloma, and found that higher level of LILRB4 in CD45−/CD38+ multiple myeloma cells seems to correspond to a tendency towards more RELT level in serum." (PMID 38951916, 2024). "Mechanistically, fibronectin or apoE binding to LILRB4 recruited p-SHP2 to activate NF-κB signal pathway, then promoted multiple myeloma cells to secret RELT." (PMID 38951916, 2024). "For example, RELT is a good prognostic indicator for small-cell lung cancer, yet conversely, it can promote NF-κB activation in multiple myeloma cells and in ESCC and inhibit Caspase 3 cleavage in ESCC." (PMID 39767574, 2024). "RELT also promotes bone lesions in multiple myeloma cells through the activation of NF-κB." (PMID 39767574, 2024). "Our data supported that LILRB4 signal pathway promoted the differentiation and mature of osteoclasts by secreting RELT, and LILRB4 had the potential to be a new target for the treatment of multiple myeloma." (PMID 38951916, 2024). "LILRB4 did not affect the proliferation and metastasis of multiple myeloma, but LILRB4 blocking antibody could prevent the binding of LILRB4 to its ligands, therefore, anti-LILRB4 could block its signal pathway to inhibit the RELT secretion, then alleviate bone damage." (PMID 38951916, 2024).
prostate carcinoma (2 papers, 2023 to 2025). A carcinoma that arises from epithelial cells of the prostate gland. "RELT acts in PRAD (prostate cancer) by correlating with the expression of immune checkpoints and dysfunction of T cells, dendritic cells, and neutrophils." (PMID 41376629, 2025). "RELT was one of five signature genes that predicted poor prognosis for prostate cancer patients." (PMID 37893069, 2023). "RELT expression in prostate cancer correlated significantly with Tregs, dendritic cells, myeloid-derived suppressor cells, and dendritic cells, indicating that RELT may promote an immunosuppressive environment." (PMID 37893069, 2023). "Furthermore, this study identified RELT as a member of a 13-gene panel, SigIQGAP3NW, that predicts poor outcomes for prostate cancer." (PMID 37893069, 2023). "An additional bioinformatic study demonstrated a correlation of RELT expression with IQGAP3, a protein that influences cytoskeleton dynamics and poor prognosis for prostate cancer patients." (PMID 37893069, 2023). "RELT expression correlates strongly with many immune checkpoint blockade (ICBs) targets such as CTLA-4, TGF-β, PD-L2, in many cancers such as renal cell carcinoma and prostate cancer." (PMID 37893069, 2023).
renal carcinoma (2 papers, 2024 to 2025). A carcinoma arising from the epithelium of the renal parenchyma or the renal pelvis. "Bioinformatic analysis indicates that RELT is a poor prognostic indicator for renal cancer, head and neck cancer, and prostate cancer." (PMID 39767574, 2024). "Meanwhile, functional assays proved that shRELT could inhibit the migration ability and invasion ability of renal cancer cells, whereas RELT overexpression promoted invasion and migration of renal cell carcinoma cells." (PMID 41376629, 2025). "Furthermore, bioinformatic analysis examining the relationship of RELT with both prostate and renal cancer also indicates that RELT may promote an immunosuppressive environment that favors the tumor." (PMID 39767574, 2024).
colon adenocarcinoma (1 paper, 2023). "A reduced tumor growth rate and an increased number of infiltrating CD8+ lymphocytes were observed when MC38 colon adenocarcinoma cells were injected into RELT−/− mice in comparison to control mice, indicating that RELT counters the tumor-killing ability of CD8+ cells." (PMID 37893069, 2023).
esophageal cancer (1 paper, 2023). A primary or metastatic malignant neoplasm involving the esophagus. "Inhibitors of NF-κB negated the pro-survival effects of RELT expression in esophageal cancer cells, and knockdown of RELT expression in mice decreased the nuclear localization of NF-κB in vivo." (PMID 37893069, 2023). "RELT expression was correlated with increased cell proliferation and nuclear localization of NF-κB in esophageal cancer cell lines." (PMID 37893069, 2023).
glioma (1 paper, 2021). A benign or malignant brain and spinal cord tumor that arises from glial cells (astrocytes, oligodendrocytes, ependymal cells). "RELT is significantly upregulated in glioma and is associated with a poor prognosis." (PMID 34537809, 2021).
head and neck squamous cell carcinoma (1 paper, 2023). A squamous cell carcinoma that arises from any of the following anatomic sites: lip and oral cavity, nasal cavity, paranasal sinuses, pharynx, larynx, and salivary glands. "RELT expression is suppressed by miR-424-5p in head and neck squamous cell carcinoma (HNSC) patients, and interestingly, RELT expression was also suppressed by a variety of chemotherapeutic agents in HNSC patients." (PMID 37893069, 2023).
helminth infection (1 paper, 2023). "The RELT promoter region in primary immune cells is hypermethylated in response to helminth infection, which is consistent with RELT functioning to inhibit T-cell responses to infection." (PMID 37893069, 2023).
high blood pressure (1 paper, 2023). "The SNP rs75612301 associated with high blood pressure was positively correlated with RELT expression, though a direct correlation between RELT and high blood pressure is currently lacking." (PMID 37893069, 2023).
Lymphatic Metastasis (1 paper, 2021). Transfer of a neoplasm from its primary site to lymph nodes or to distant parts of the body by way of the lymphatic system. "The expression levels of RELT, TNFSF18, and TNFRSF25 were high, and the expression levels of EDA2R were low in patients with lymphatic metastasis." (PMID 34484286, 2021).
melanoma (1 paper, 2023). A malignant, usually aggressive tumor composed of atypical, neoplastic melanocytes. "RELT was also abundantly transcribed in cervical cancer cells (HeLa) yet was not abundantly expressed in colorectal (SW480), lung (A549), or melanoma (G361) cells." (PMID 37893069, 2023). "Mice harboring B16–10 melanoma cells exhibited a greater number of infiltrating tumor-specific CD8+ T cells and a reduced tumor growth rate after being infused with naïve RELT−/− CD8+ T cells in comparison to naïve WT CD8+ T cells." (PMID 37893069, 2023).
non-small cell lung carcinoma (1 paper, 2023). A group of at least three distinct histological types of lung cancer, including non-small cell squamous cell carcinoma, adenocarcinoma, and large cell carcinoma. "Microarray analysis demonstrated that RELT expression is upregulated in a non-small cell lung cancer cell line (A549) treated with the glucocorticoid dexamethasone." (PMID 37893069, 2023). "RELT mRNA was found to be upregulated in the lung tumors versus non-malignant tissue of four patients; most (16 out of 19) patients in this study had non-small cell lung cancer (NSCLC)." (PMID 37893069, 2023).
pancreatitis (1 paper, 2023). Inflammation of the pancreas. "The cells were sorted into cells undergoing apoptosis versus oncosis, and RELT protein was exclusively associated with the apoptotic population, suggesting that RELT may participate in the induction of apoptosis of acinar cells in pancreatitis." (PMID 37893069, 2023). "Data utilizing the cell line AR42J indicate RELT promotes apoptosis after stimulation of pancreatic acinar cells with caerulein, a peptide utilized to induce pancreatitis in mouse models." (PMID 37893069, 2023).
small cell lung carcinoma (1 paper, 2024). Small cell lung cancer (SCLC) is a highly aggressive malignant neoplasm, accounting for 10-15% of lung cancer cases, characterized byrapid growth, and early metastasis. "Conversely, bioinformatic analysis predicts that RELT is protective against small-cell lung cancer." (PMID 39767574, 2024).